NKX2-1 (NK2 homeobox 1)
Diseases named in the same sentence as NKX2-1 in open-access papers (continued):
Sharing a sentence is not in itself a finding about the gene and the disease.
squamous cell carcinoma (24 papers, 2012 to 2025). A carcinoma arising from squamous epithelial cells. "Mollaoglu's study supports this notion, proposing that in the transformation from adenocarcinoma to squamous carcinoma, the deletion of NKX2‐1 or overexpression of SOX2 recruits tumour‐associated neutrophils, with the CXCL5 chemokine further promoting SOX2‐driven squamous cell transformation." (PMID 40847555, 2025). "Loss of NKX2-1 could led to tumor-associated neutrophils recruitment to shape the immune microenvironment suitable for the survival of squamous carcinoma, which in turn promotes the development of squamous carcinoma." (PMID 38708353, 2024). "Previous work has found that completely deleting Nkx2-1 leads to a model that produces mucinous adenocarcinomas and adenosquamous and squamous cell carcinomas." (PMID 40327401, 2025). "Coupled SOX2 overexpression in the context of NKX2‐1 deletion facilitates the formation of squamous carcinomas with oesophageal differentiation traits, though this is typically a transient stage or branch." (PMID 40847555, 2025). "The transcription factors TTF1/NKX2-1 and ΔNp63/p40 are the counterposed molecular markers associated with the main Non-Small Cell Lung Cancer subtypes: TTF1 for adenocarcinoma, p40 for squamous cell carcinoma." (PMID 38291083, 2024). "NKX2–1 expression was also significantly higher in patients with ADK than in those with squamous cell carcinoma (SCC) (P < 0.001)." (PMID 29237428, 2017). "For instance, TFs such as SOX2 and NKX2‐1 are crucial in mediating the transformation of LUAD to squamous carcinoma, while epigenetic regulators like EZH2 and LSD1 influence tumour cell differentiation and proliferation by modulating histone modifications and DNA methylation." (PMID 40847555, 2025). "It is interesting to note that although the secretory subtype is a squamous cell carcinoma subtype, it shows intermediate scores in the Adenocarcinoma factor, which is consistent with the fact that NKX2-1 is expressed in both the Secretory subtype and in adenocarcinomas." (PMID 30379847, 2018). "However, cytoplasmic staining of the NKX2-1 protein and expression of the NKX2-1 transcript has been observed in squamous cell carcinomas." (PMID 23497426, 2013). "We found that USP13 altered lineage-determining factors such as NKX2-1 and SOX2 in club cells of the airway and reinforced the fate of club cells to squamous carcinoma development." (PMID 38093367, 2023). "Squamous cell carcinomas are typically negative for nuclear NKX2-1 protein expression." (PMID 23497426, 2013).
thyroid (24 papers, 2008 to 2025). "Other genes implicated in syndromic CDH include NK2 homeobox 1 (NKX2-1), which is associated with thyroid dysgenesis and respiratory issues, and SRY-box transcription factor 9 (SOX9), which is involved in sex determination and cartilage formation." (PMID 40710310, 2025). "For instance, NKX2–1 molecular defects are often linked to thyroid and neurological disorders, necessitating specific expertise." (PMID 40134350, 2025). "It is argued that this is not necessarily a “benign” condition, as it is associated mainly with pulmonary and thyroid disorders in the most severe expression of the TITF1/NKX2-1-related disorders." (PMID 32832197, 2020). "For instance, NKX2–1 mutations are frequently associated with thyroid and neurological disorders, which require specific expertise." (PMID 31796085, 2019). "Differences in genetic background could explain phenotypic variations of thyroid dysgenesis although the pathogenetic mutations are identical as in Nkx2-1/Pax8 compound heterozygous mice." (PMID 29361553, 2018). "By elucidating the complexities of NKX2-1-RD, our research highlights the criticality of evaluating thyroid function in the context of neonatal respiratory distress syndrome (RDS), specifically among females." (PMID 40395234, 2025). "According to previous reports, the cause of CH in approximately 80%–85% of patients is thyroid dysgenesis (including agenesis, ectopy, and hypoplasia), which is related to gene mutations in TSHR, PAX8, TTF1/NKX2-1, and TTF2/FOXE1." (PMID 37252044, 2023). "The genes associated with thyroid morphogenesis such as NKX2-1, NKX2-5, PAX8, FOXE1, and thyroid-stimulating hormone receptor (TSHR) have been reported to be involved in thyroid dysgenesis." (PMID 32394050, 2020).
brain-lung-thyroid syndrome (19 papers, 2011 to 2025). Brain-lung-thyroid syndrome is a rare disorder characterized by congenital hypothyroidism (CH), infant respiratory distress syndrome (IRDS) and benign hereditary chorea (BHC). "NKX2-1 mutations underlie Brain-Thyroid-Lung syndrome, a rare genetic disease, that is almost always characterized by congenital hypothyroidism." (PMID 33959101, 2021). "Brain-lung-thyroid syndrome is cause by mutation of the NKX2-1 gene, which causes the destruction of major organs, that is, the lungs, thyroid glands, and nervous system." (PMID 32195974, 2020). "Mutations of the NKX2-1 gene are associated with brain-lung-thyroid syndrome, which is characterized by benign hereditary chorea, hypothyroidism, and pulmonary disease with variable presentation." (PMID 32195974, 2020). "Loss-of-function mutations in NKX2-1, a gene vital to the normal development and function of the brain, lungs, and thyroid, have been identified, leading to the description of a “brain-lung-thyroid syndrome” in some cases." (PMID 26933606, 2015). "Genetic complications impacting on the thyroid-basal ganglia interaction may also play a role, as observed in the Brain-Lung-Thyroid Syndrome, linked to mutations in NKX2-1." (PMID 39070061, 2024). "In a study and report from the University of Cardiff and other centers in the UK, of 10 probands with BHC and NKX2-1 mutations, 8 presented with muscle hypotonia and 4 with hypothyroidism; only 3 of the 10 cases had the full triad of “brain-lung-thyroid syndrome." (PMID 26933606, 2015). "Two patients showed a brain lung thyroid syndrome with TITF1/NKX2-1 mutation." (PMID 22704798, 2012). "The most frequently reported symptoms are related to the central nervous system, lungs, and thyroid gland, hence the clinical term NKX2-1-related disorders - “brain-lung-thyroid syndrome”." (PMID 38916623, 2024). "Case #13A was found to be a carrier of a benign NKX2-1 heterozygous variant (p.A116D) lacking the typical extrathyroidal manifestations of Brain-Lung-Thyroid syndrome." (PMID 36071330, 2023). "In humans, autosomal dominant NKX2-1 pathogenic variants are associated with brain-lung-thyroid syndrome (BLTS), but not always: there is a large variability in the phenotype presentation that may exclude any of the three phenotypes in BLTS." (PMID 36733766, 2022).
hypothyroidism (18 papers, 2010 to 2025). Abnormally low levels of thyroid hormone. "In conclusion, previously published reports have shown that NKX2-1-mutation was associated with phenotypic variation and a spectrum of clinical manifestations including benign hereditary chorea, hypothyroidism, chronic ILD, and respiratory distress syndrome." (PMID 32195974, 2020). "Heterozygous mutations of thyroid enriched master regulators, such as Pax8 and Nkx2-1, have been associated to different grades of human hypothyroidism." (PMID 30397221, 2018). "In mouse, stronger effects were related to earlier exposure or specific genetic background such as either Pax8 or Nkx2-1 haploinsufficiency, both associated to hypothyroidism in humans." (PMID 30397221, 2018). "NKX2-1-disorders are associated with choreoathetosis and hypothyroidism." (PMID 33806661, 2021). "Besides the novel mutation of NKX2-1, the patient also presented with mild hypothyroidism and neurological symptoms." (PMID 32195974, 2020). "Indeed, the TCDD exposure was worsened in genetic context characterized by haploinsufficiency of Pax8+/− or Nkx2-1+/−, genetic conditions, associated with hypothyroidism in humans." (PMID 30397221, 2018). "Lung disorders, hypothyroidism, and central nervous system abnormalities affect 54%, 87%, and 93% of NKX2-1-RD patients." (PMID 38990976, 2024). "The follow-up of patients with NKX2-1-RD and hypothyroidism is more common during childhood and early adolescence, when symptoms of NKX2-1-RD become evident from birth." (PMID 39466809, 2024). "Adhering to PRISMA guidelines, the review includes 42 studies involving 110 genetically confirmed NKX2-1-RD patients with hypothyroidism." (PMID 39466809, 2024). "Due to the complexity of NKX2-1-RD, the frequency of the follow-up also depended on the resolution of the hypothyroidism and the severity of other clinical manifestations such as neurological and/or respiratory alterations." (PMID 39466809, 2024). "Only patients with genetic confirmation of NKX2-1-RD and hypothyroidism were included to ensure internal validity." (PMID 38990976, 2024). "In these genes, NKX2-1 deletion is responsible for choreoathetosis, hypothyroidism, and neonatal respiratory distress and haploinsufficiency of PAX9 causes oligodontia phenotype." (PMID 32595695, 2020). "Nkx2-1 and Pax8 double heterozygous mice of 129/Sv genetic background display thyroid hemiagenesis and hypothyroidism, indicating a polygenic origin of the thyroid hemiagenesis." (PMID 31465501, 2019). "Considering the hypothyroidism phenotype present only in Nkx2‐1−/− or Pax8−/− or double Nkx2‐1+/−Pax8+/− mice, we decided to study directly the knock‐out mice." (PMID 30446499, 2018). "In addition to hypothyroidism, the presence of other endocrine alterations was found among the patients with NKX2-1-RD." (PMID 38990976, 2024). "While there is not a clear pathophysiological basis to corroborate this finding specifically in patients with NKX2-1-RD hypothyroidism, it prompts a crucial consideration for the management of CH cases, particularly those associated with NKX2-1 pathogenic variants or deletions." (PMID 39466809, 2024). "Despite its lack of specificity, thyroid agenesis in Nkx2-1 knockout mice and pediatric hypothyroidism in humans born with NKX2-1 mutations further highlight the importance of Nkx2-1 as a key regulator of thyroid organogenesis." (PMID 24995001, 2014). "The combination of hypothyroidism, moderate respiratory problems and motor control problems suggested the possibility of TITF1/NKX2-1 haploinsufficiency." (PMID 22155464, 2011). "It is important to note that these considerations are general parameters applicable to CH and are not specific to NKX2-1-RD patients, as they are already encompassed in existing guidelines for the treatment of hypothyroidism." (PMID 39466809, 2024).
hypothyroidism (continued). "NKX2-1-RD exhibit a diverse range of phenotypes, ranging from CH detected in infancy to cases diagnosed later in childhood or adulthood, as well as compensated hypothyroidism that does not necessitate treatment." (PMID 39466809, 2024).
non-small cell lung carcinoma (17 papers, 2010 to 2025). A group of at least three distinct histological types of lung cancer, including non-small cell squamous cell carcinoma, adenocarcinoma, and large cell carcinoma. "NKX2-1, encoding a homeobox transcription factor, is amplified in approximately 15% of non-small cell lung cancers (NSCLC), where it is thought to drive cancer cell proliferation and survival." (PMID 26556242, 2015). "In addition, NKX2-1 transduction increases cellular apoptosis in non-small cell lung cancer, suggesting that it might serve as a tumor suppressor gene." (PMID 34748583, 2021).
thyroid tumor (17 papers, 2010 to 2025). A benign or malignant neoplasm affecting the thyroid gland. "Gain- and loss-of-function assays revealed that DICER1 regulates NKX2-1 expression in thyroid tumor cells and vice versa, thus establishing a positive feedback loop between both proteins." (PMID 33176626, 2021). "On the other hand, Tshr, Pax8 and Nkx2-1 mRNA expressions remained unaltered in thyroid tumors compared to WT thyroids in 2- and 8-month-old mice." (PMID 41002430, 2025). "We found that PAX8 and NKX2-1 levels are significantly reduced in DICER1-silenced human thyroid tumor cells, whereas the opposite is seen in DICER1 overexpressing cells." (PMID 33176626, 2021). "We observed that NKX2-1 expression was lower in thyroid tumor tissue than in paired normal tissue, which is consistent with the described loss of differentiation." (PMID 33176626, 2021). "As lower expression of NKX2-1 is correlated with progressive dedifferentiation of thyroid tumors, we next used qPCR to evaluate the expression levels of NKX2-1 in thyroid samples and correlated NKX2-1 and ABI3 expression." (PMID 27036019, 2016). "Next, we investigated immunocytochemically whether NKX2-1 expression in thyroid tumors might be affected similar to early neoplastic lung lesions." (PMID 37534159, 2023). "Although the level of NKX2-1 expression was comparable in thyroid tumors, a positive correlation was observed between ABI3 and NKX2-1 expression in thyroid tumors (r = 0.4057 and P = 0.0179)." (PMID 27036019, 2016). "Thus, although thyroid tumor cells eventually regained NKX2-1 expression, downregulation of NKX2-1 was restricted to a subpopulation of cells located close to sites of tumor initiation in Nkx2.1-CreERT2;BrafCA/+ mice." (PMID 37534159, 2023). "We also found a positive correlation between NKX2-1 and DICER1 expression in human thyroid tumors." (PMID 33176626, 2021).
congenital hypothyroidism (16 papers, 2010 to 2024). A thyroid hormone deficiency present from birth. "Studies have demonstrated that NKX2-1 gene mutations related to compensated congenital hypothyroidism and unexplained respiratory distress due to lung hypoplasia in neonates." (PMID 36203529, 2022). "In addition, Nkx2-1 is associated with several diseases, including benign hereditary chorea, choreoathetosis, congenital hypothyroidism, and neonatal respiratory distress." (PMID 34828268, 2021). "We reported a fatal outcome in an infant with ILD, persistent low oxyhemoglobin saturation, congenital hypothyroidism, feeding difficulty, irritability, and convulsion, which constitute NKX2-1-related disorders." (PMID 32195974, 2020). "We identified a novel mutation of NKX2-1 combined with SFTPC mutation in a term male infant with ILD, persistent low oxyhemoglobin saturation, congenital hypothyroidism, feeding difficulty, irritability, and convulsion." (PMID 32195974, 2020). "We report a case of congenital hypothyroidism (CH) with neurological and respiratory alterations due to a heterozygotic c.374-1G > A mutation of TITF1/NKX2-1." (PMID 22155464, 2011).
papillary thyroid carcinoma (15 papers, 2003 to 2023). "A human papillary thyroid carcinoma cell line lacking NKX2-1 expression was infected with an adenoviral vector containing Nkx2-1." (PMID 34748583, 2021).
breast carcinoma (14 papers, 2008 to 2025). "NKX2-1 has previously been identified as a marker to distinguish breast cancer from other types of cancer." (PMID 32051475, 2020). "This factor is involved in ESR1-mediated transcription (required for ESR1 binding to the NKX2-1 promoter in breast cancer cells), of the RPRM promoter, needed for estrogen-induced repression in these cells." (PMID 29290962, 2017).
mucinous adenocarcinoma (14 papers, 2015 to 2025). An invasive adenocarcinoma composed of malignant glandular cells which contain intracytoplasmic mucin. "Transgenic mice with inactivated Nkx2-1/Ttf-1 develop mucinous adenocarcinomas in the lungs that resemble human IMAs." (PMID 34290355, 2022). "In contrast to vehicle controls, Nkx2-1 deletion drove transition of established tumors to invasive mucinous adenocarcinoma (IMA)." (PMID 33821796, 2021). "In contrast, NKX2-1-positive LUAD showed a trend toward lower pERK staining than the mucinous adenocarcinomas." (PMID 33821796, 2021). "pointed out that the respiratory epithelium in mouse with only oncogenic Kras G12D cannot induce mucinous adenocarcinoma; only when Nkx2‐1 expression is reduced (haploinsufficiency) and Kras^G12D is present can lesions resembling human mucinous adenocarcinoma form." (PMID 40847555, 2025). "Nkx2-1 deletion in established BRAF-mutant LUAD induces mucinous adenocarcinoma without altering tumor growth." (PMID 33821796, 2021).
Chorea (13 papers, 2014 to 2025). Chorea (Greek for 'dance') refers to widespread arrhythmic involuntary movements of a forcible, jerky and restless fashion. "The NKX2-1 mutation should always be considered as a potential diagnosis in families with chorea, even with a family history of HD." (PMID 38916623, 2024). "There is a wide spectrum of neurological cases with NKX2-1 gene mutations, demonstrating a need for a thorough differential diagnosis in patients with chorea." (PMID 38916623, 2024). "Interestingly, mutations in the NKX2-1 gene, which encodes for a protein that regulates the expression of thyroid-specific genes, cause benign hereditary chorea, a characteristic symptom of HD." (PMID 33663567, 2021). "Benign hereditary chorea (BHC) is a rare childhood-onset hyperkinetic disorder caused by pathogenic variants in NKX2-1." (PMID 41423511, 2025). "The literature identified conditions linked to variants of the NKX2-1, SLC16A2, and ATM genes as causes of the chorea phenotype associated with multisystem impairment." (PMID 38921008, 2024). "Chorea and choreiform movements occurred in 84.3% of the patients, making it the most common symptom of NKX2-1-related disorders, which is why it is described in the literature as benign hereditary chorea." (PMID 38916623, 2024). "Infantile chorea and its possible association with thyroid or lung disease may aid in differentiating BHC from other similar hereditary movement diseases, and patients should be proactively tested for NKX2-1 gene mutations." (PMID 36936169, 2023). "Pathogenic variants in NKX2-1 typically act through haploinsufficiency, resulting in a broad phenotypic spectrum ranging from isolated non-progressive chorea to congenital hypothyroidism and respiratory disease." (PMID 41423511, 2025). "This case illustrates that a positive family history for HD does not exclude other causes of chorea as a possible diagnosis, including an NKX2-1-related disorder." (PMID 38916623, 2024). "Moreover, there is an example in the literature of a 49-year-old patient with the NKX2-1 mutation who presented with ataxic gait, but chorea had still not occurred." (PMID 38916623, 2024). "Chorea is the major phenotypic aspect of Huntington’s disease (HD) (OMIM #143,100) as well as other Huntington-like syndromes and benign hereditary chorea (BHC) – a clinical manifestation of the NKX2-1-related disorders." (PMID 38916623, 2024). "NKX2-1-related disorder, or benign hereditary chorea (BHC), is a rare disorder encompassing heterogeneous clinical features, characterized by childhood-onset chorea, combined with other neurological, pulmonary, and endocrinological abnormalities." (PMID 38921008, 2024). "Also, a minority of patients with NKX2‐1 defects showed a pure chorea phenotype." (PMID 36054588, 2022). "Lack of chorea does not always exclude the diagnosis of NKX2-1-related disorders, so the term “benign hereditary chorea” is not always accurate and should be avoided." (PMID 38916623, 2024). "According to OMIM, both BHC (OMIM #118,700), chorea, congenital hypothyroidism with or without pulmonary dysfunction (CAHTP, OMIM #610,978); and susceptibility to nonmedullary thyroid cancer-1 (NMTC1, OMIM #188,550), are related to mutations in the NKX2-1 gene." (PMID 38916623, 2024). "Lack of chorea does not exclude the NKX2-1-related disorders." (PMID 38916623, 2024).